HMGB1 (high mobility group box 1)
Diseases named in the same sentence as HMGB1 in open-access papers (continued):
Sharing a sentence is not in itself a finding about the gene and the disease.
tumor (continued). "One of the main targets of HMGB1 turned out to be the mitochondrial energy metabolism as tumour cells devoid of a functioning mitochondrial respiratory chain were resistant to HMGB1 cytotoxicity." (PMID 26948869, 2016). "Anthracyclines, in particular, induce tumour cell damage and exposure of calreticulin and other endoplasmic reticulum proteins, secretion of ATP, and release of the high-mobility group box 1 (HMGB1) molecules." (PMID 27777963, 2016). "Elevated levels of HMGB1 have been reported for numerous cancers, including CRC, and higher levels of HMGB1 has been show to positively correlate with tumour invasion and metastasis (both distant and lymph-node), and reduced survival for CRC patients." (PMID 27323825, 2016). "HMGB1 can be passively released from necrotic, autophagic, and apoptotic cells or actively secreted from oncogene-activated tumor cells." (PMID 27493669, 2016). "Western blot analysis revealed that HMGB1 expression was significantly suppressed in the stable knocked down cells and subcutaneous tumor generated from these cells, which is consistent with the effect in vitro." (PMID 26499944, 2016). "High HMGB1 expression was detected in 94 (63.1 %) of the tumor tissues and in 59 (39.6 %) of the paired paratumoral tissues." (PMID 27836008, 2016). "The inflammatory tumor microenvironment (TME) induces HMGB1 release by infiltrating leukocytes and the cancer cells themselves." (PMID 26925422, 2016). "During inflammation, cell migration and tumor metastases, HMGB1 serves as an extracellular cytokine and mediates a series of signaling molecules by binding to its membrane receptors, including RAGE, TLR4 and TLR2." (PMID 27899819, 2016). "Accordingly, neutralizing HMGB1 antibody or RAGE knockdown inhibited tumor angiogenesis and metastasis in vitro and in vivo." (PMID 27493669, 2016). "Released from certain cells, including cancer cells, HMGB1 plays important roles in inflammation and tumor metastasis." (PMID 26989079, 2016). "Other released DAMPs resulted from tumor necrosis, such as ATP, calreticulin, and HMGB1 would be worthy further investigating." (PMID 27256519, 2016). "Our results also demonstrated a correlation between HMGB1 overexpression in HCC tumor tissues and poor OS." (PMID 27836008, 2016). "Conversely, tumor cell-derived HMGB1 was shown to suppress CD8+ T cells antitumor immunity through the induction of IL-10-producing Tregs." (PMID 27917371, 2016). "In this context we also discuss HMGB1 as a possible key-player linking NK cells to the plasticity of tumor cells." (PMID 27294158, 2016). "Functional assay indicated that SNP rs1045411 genotypes had a significant influence on mRNA expression of HMGB1 in GC tissues as well as two tumor cell lines." (PMID 27116470, 2016). "Taken together, these results are supportive of a tumour-promoting role for HMGB1 dependent on its ability to induce IL-10 secretion by M2-like macrophages in a RAGE-dependent manner." (PMID 27426915, 2016). "If cancer cells do not cope with redox imbalance and undergone necrosis, the released HMGB1 induces diverse responses over the cells in the microenvironment, which contribute to tumour cell survival and the development of metastases." (PMID 26682011, 2016). "We demonstrated that dying tumor cells under DTX treatment release HMGB1 as a danger signal that binds TLR and RAGE on the neighboring live remnant tumor cells to trigger sCLU induction." (PMID 27405665, 2016). "The next step was to test the expression of few EMT-related proteins, as well as of HMGB1, in tumor tissue sections from hCD31 treated and control mice." (PMID 26925422, 2016). "Curiously, oncogenic and tumour-suppressive activities have been assigned to HMGB1 at different stages of tumour genesis and therapy." (PMID 26682011, 2016). "HMGB1 also interacts with topoisomerase II alpha, highly expressed in tumours and involved in replication and chromosomal segregation and recombination, and stimulates its catalytic activity." (PMID 26682011, 2016).
tumor (continued). "To monitor a potential release of HMGB1 from dying tumor cells in response to the first chemotherapeutic cycle, we collected an additional blood sample in the days after the initial dose of chemotherapy." (PMID 27457217, 2016). "HMGB1 release by dying tumor cells can lead to the activation of DCs and prevention of tumor progression." (PMID 27177220, 2016). "As tumor necrosis was observed by H&E stain, this phenotype was further confirmed by HMGB1 immunostaining." (PMID 27283985, 2016). "This suggests that through autocrine/paracrine binding to these RAGE receptors, Ac-HMGB1 activates NF-κB signaling and promotes survival of these hypoxic GemOE tumor cells within tumor cores." (PMID 26989079, 2016). "In line with these experimental results, high HMGB1 levels in primary tumor tissues correlate with low intratumoral CD205+ DCs." (PMID 27917371, 2016). "One report from Korea demonstrated that PPAR-γ activated by rosiglitazone was involved in the inhibition of lipopolysaccharide- (LPS-) induced HMGB1 release in RAW264.7 cells (macrophages from Abelson murine leukemia virus-induced tumor)." (PMID 27563308, 2016). "HMGB1 treatment decreased the turn-over of oxygen as demonstrated by a potent inhibition of COX activity in the primary tumour tissue." (PMID 26948869, 2016). "It has been suggested that HMGB1 functions as a potentially oncogenic protein to promote tumor progress, and its overexpression in cancer cells affects the anti-cancer T-cell response through activation of intracellular signaling." (PMID 27116470, 2016). "The process of inflammation driven intestinal repair is known to promote a tumour-promoting environment, and the release of HMGB1 contributes to tumourigenesis in mouse models of colitis-associated cancer." (PMID 27323825, 2016). "HMGB1 dampens antitumor immunity by inducing apoptosis of macrophage-derived DCs and suppressing tumor specific CD8+ T cell effectors in part through the induction of IL-10 production by T regulatory cells." (PMID 26925422, 2016). "As the functions of HMGB1 depend on the subcellular locations, its influence on tumor development and progression ought to be explained by different models." (PMID 27391431, 2016). "Extracellular reduced HMGB1 induces autophagy and tumor growth through RAGE, whereas oxidized HMGB1 triggers apoptosis of cancer cells." (PMID 26925422, 2016). "Compared to Ca-TAT/control siRNA treatment, Ca-TAT delivery of either CCL2 siRNAs reduced HMGB1 in the primary tumor by over 75%, further demonstrating increased necrosis in the primary tumor with CCL2 gene silencing." (PMID 27283985, 2016). "In accordance with results observed with HMGB1 silencing using shRNA, systemic treatment of tumour-bearing mice with the HMGB1 inhibitor BoxA also resulted in significantly delayed tumour growth compared to mice exposed to vehicle alone." (PMID 27426915, 2016). "High-mobility group protein box1 (HMGB1) is a pivotal factor in the development and progression of many types of tumor." (PMID 27836008, 2016). "The peritumoral HMGB1 expression levels were correlated with tumor invasiveness, BCLC stage, and recurrence." (PMID 27836008, 2016). "Endogenous danger associated molecular pattern (DAMP’s) like heparan sulphate, heat shock proteins, HMGB1, hyaluronic acid are released from dying tumor cells which serve as ligands for various TLR’s within tumor microenvironment." (PMID 27511884, 2016). "It is possible that components from dying tumor cells such as ATP, HMGB1, or oxidized DNA induce the activation of NLRP3 inflammasome." (PMID 27786298, 2016). "In the current study, we show geminin-dependent acetylation and extracellular secretion of chromatin-bound HMGB1 from necrotic/hypoxic GemOE in tumor cores." (PMID 26989079, 2016). "We demonstrate that HMGB1 released by hypoxic tumour cells favours the accumulation of M2-like macrophages at the tumour site and their secretion of IL-10." (PMID 27426915, 2016).
tumor (continued). "In OSCC, MIA is upregulated by intracellular HMGB1 and NFkB p65 and promotes tumor progression and nodal metastasis by inducing VEGF family-mediated upregulation of angiogenesis and lymphangiogenesis." (PMID 27050375, 2016). "We recently described that recombinant human HMGB1 efficiently induces a novel form of cell death in tumour cells." (PMID 26948869, 2016). "Here, we show that the alarmin HMGB1, which is released from tumour cells under hypoxic conditions, plays a critical role in promoting tumour progression by triggering the accumulation of M2-like TAMs." (PMID 27426915, 2016). "In line, the interaction of HMGB1 with the receptor for advanced glycation end products (RAGE) that is expressed on various cell lines in the tumor increases chemo resistance by inducing pro-survival autophagy." (PMID 27933272, 2016). "Blockade of HMGB1-RAGE-MAPK signaling has been demonstrated to suppress tumor growth and metastasis." (PMID 26499944, 2016). "Both Hmgb1 and LPS, an immune system activation factor, can activate NF-κB and subsequently promote tumor development." (PMID 27779100, 2016). "HMGB1 expression in the peritumoral liver tissues was strongly correlated with higher histological grades and tumor invasiveness, whereas HMGB1 expression in the tumors was only correlated marginally with recurrence and higher BCLC stage." (PMID 27836008, 2016). "Recently, it was observed that HMGB1 was selectively released from tumor cells undergoing autophagy." (PMID 25652880, 2015). "During immunogenic cell death, dying tumor cells release danger signals such as adenosine triphosphate (ATP) and high-mobility group protein B1 (HMGB1), which act to prime an antitumor immune response." (PMID 26300242, 2015). "We further show that TLR-5 plays a role in upregulation of the alarmin HMGB1 (High Mobility Group Box 1) in wound-induced mouse tumours and demonstrate that HMGB1 is also elevated in tumours of RDEB patients." (PMID 25575023, 2015). "In the presence of later DAMPs, such as HMGB1, the internalized tumor antigens get processed and cross-presented finally resulting in stimulation of tumor-specific CTLs." (PMID 26500646, 2015). "It is important to verify that the induction of sCLU by HMGB1 can be translated into tumor survival and resistance to DTX treatment." (PMID 26469759, 2015). "Further, knock-down of HMGB-1 inhibited the potential of irradiated tumor cells to stimulate dendritic cells." (PMID 25688334, 2015). "We reproduced the same results when supernatants from DTX-treated DU145 tumor cells were substituted for recombinant HMGB1." (PMID 26469759, 2015). "Given the emerging importance of HMGB1 and its tumor-promoting functions in many cancer types, and of aspirin in cancer prevention and therapy, our investigation is poised to provide broadly applicable information." (PMID 26068794, 2015). "Use of both anti-TLR4 and anti-RAGE had a more deleterious effect on tumor cells, suggesting that both receptors confer HMGB1-mediated drug resistance to DTX." (PMID 26469759, 2015). "Taken together, we presume that antioxidants or inhibitors against different redox forms of HMGB1 should be better methods than oxidants to inhibit the HMGB1-induced tumour angiogenesis." (PMID 26099505, 2015). "HMGB1 exerts multiple proinflammatory functions in this tumor microenvironment, including activation and induction of proinflammatory cytokines (via NF-κB), the interaction with cytokines like IL-1β and the promotion of angiogenesis and metastasis." (PMID 26854151, 2015). "In several animal models, blockade of HMGB1 has decreased pathologic angiogenesis and the inhibition of tumour growth and metastasis 11,33,35." (PMID 26099505, 2015).
tumor (continued). "Functional inhibition of HMGB1 and its receptors abrogated HMGB1-induced angiogenic properties of ECs co-cultured with tumour cells." (PMID 26099505, 2015). "HMGB1 has been shown to stimulate mature dendritic cells to degrade tumor antigen processing through its interaction with TLR-4." (PMID 25622595, 2015). "In conclusion, our available experimental evidence suggest a dual role of HMGB1 in tumour angiogenesis: recruitment of ECs and their activation to secrete pro-angiogenic factor VEGF-A, which depends on distinct redox states of the same protein." (PMID 26099505, 2015). "HMGB1 orchestrates the key events of tumour angiogenesis, migration of ECs and their induction to secrete VEGF-A, by adopting distinct redox states." (PMID 26099505, 2015). "HMGB1 was positively expressed in 90 % of cells in all tumor stages and across our selected CRC samples." (PMID 26388988, 2015). "Fifteen BUC tissues and paired adjacent non-tumour tissues were used to detect the expression of HMGB1." (PMID 26239046, 2015). "The DU145 tumor cells were thus treated with 2 different doses of recombinant HMGB1 for 24–48 h and assessed for sCLU production." (PMID 26469759, 2015). "The release of HMGB1 by dying cancer cells is mandatory to license host DCs to process and present tumor antigens." (PMID 26315113, 2015). "HMGB1 was predominantly localized in the tumor cell cytoplasm, while low expression was detected mainly in the peritumor cell nuclei." (PMID 25652880, 2015). "TLR4 binds HMGB1 what prevents tumor antigens digestion and facilitates their trafficking to the dedicated antigen-presenting compartment." (PMID 25801067, 2015). "Blocking apoptosis and consecutive secondary necrosis in MDA-MB231 by zVAD-fmk decreased HMGB1 in the supernatants of the tumor cells." (PMID 26383236, 2015). "The cleaved caspase-3 (CC3) in irradiated tumor cells and HMGB1 in the supernatant of irradiated tumor cells were detected by Western blot." (PMID 25986235, 2015). "All in all, HMGB1 was clearly shown to interact in manifold and sometimes diverse ways in tumor development." (PMID 26854151, 2015). "Hypoxia and the maintenance of elevated levels of extracellular ATP and HMGB1 are characteristics shared between the tumor microenvironment and sites of I/R injury." (PMID 26552848, 2015). "Using prostate cancer as a focus, where acquired resistance to docetaxel (DTX) signifies a point of no return for patients, we demonstrate that DTX acts by a paracrine mechanism to promote tumor cell survival and outgrowth via a HMGB1/TLR4-RAGE/sCLU pathway." (PMID 26469759, 2015). "Tumor cells exploit HMGB1's ability to activate intracellular pathways that lead to cell growth and migration." (PMID 26106610, 2015). "To prove that sCLU production caused drug resistance, we next utilized anti-sense CLU to block its expression in DU145 tumor cells prior to treatment with HMGB1." (PMID 26469759, 2015). "While HMGB1 exerts many functions in promotion of tumor growth and was shown to be upregulated in tumor tissue early, RAGEv1 was reported to be downregulated in lung, prostate and brain tumors when compared to healthy control." (PMID 26854151, 2015). "Scrambled siRNA control transfected DU145 tumor cells were protected by recombinant HMGB1 with growth similar to medium control, even after treatment with DTX." (PMID 26469759, 2015). "X-ray radiotherapy activates tumor antigen-specific T-cell responses, and increases in the serum levels of high mobility group box 1 (HMGB1) induced by X-ray irradiation play a pivotal role in activating anti-tumor immunity." (PMID 25755254, 2015). "Anti-TLR4 and anti-RAGE pretreated tumor cells, however, lost the protective ability of HMGB1, as compared to HMGB1-treated tumor cells with control IgG." (PMID 26469759, 2015). "As a broad-spectrum tumor marker, the abnormal expression of HMGB1 contributes to the occurrence and development of numerous types of tumor." (PMID 25574225, 2015).
tumor (continued). "HMGB1 plays an important role in many processes related to tumor development and cancer growth; however, it exerts contrary functions that can be divided into pro- and anticancerogenic facets." (PMID 26854151, 2015). "In this study, the authors vaccinated mice with anthracycline- or oxaliplatin-treated cells one week prior to tumor challenge and demonstrated that antibody mediated blockade of HMGB1 compromised the efficacy of vaccination." (PMID 26486085, 2015). "When HMGB1 proteins are released in the tumor microenvironment by immune cells, they act as both autocrine and paracrine messengers." (PMID 26106610, 2015). "To further understand the contribution of extracellular HMGB1 to tumour angiogenesis, we co-cultured ECs and carcinoma cells to mimic a tumour microenvironment." (PMID 26099505, 2015). "HMGB1 can also act as an extracellular signaling molecule by promoting inflammation, tumor growth a metastasis." (PMID 26406975, 2015). "The interplay between ATP and HMGB1 appears to be essential for tumor growth, angiogenesis and metastasis." (PMID 26552848, 2015). "For this purpose, DU145 tumor cells were exposed to recombinant HMGB1 and cultured in 55 nM DTX for 48 h." (PMID 26469759, 2015). "HMGB1 serum levels further correlated positively with tumor size, T-stage, N-stage and poor outcome." (PMID 26854151, 2015). "Recently, we and others have shown that α-particle emitters 213Bi or 224Ra can induce similar ICD of tumor cells in combination with Hsp70 and HMGB-1 release, leading to efficient T-cell-dependent antitumor response." (PMID 26539436, 2015). "Expression of HMGB1 protein was significantly higher in the tumor compared to that in the peritumor tissues (P=0.0101)." (PMID 25652880, 2015). "It significantly further retarded the growth of xenogeneic tumors treated with fractionated RT (5 × 2 Gy) and increased the expression of HMGB1 as observed in tumor tissue sections." (PMID 25973681, 2015). "To elucidate the role of HMGB1 in tumour angiogenesis, we used a co-culture system that had both human ECs and tumour cells, thus avoiding inter-species complications." (PMID 26099505, 2015). "Along similar lines, the co-expression of HMGB1 in the nucleus and in the cytoplasm of malignant cells has been shown to inversely correlate with tumor infiltration by CD45RO+ memory T cells and 5-year survival rate in 72 individuals with Stage IIIB CRC." (PMID 26300886, 2015). "On the other hand, for the role in oncogenesis and progression of tumor, HMGB1 also had paradox effects." (PMID 26393575, 2015). "HMGB1 can also bind the T cell immunoglobulin- and mucin-domain containing molecule (Tim-3) that is preferentially expressed on tumor-infiltrating DCs." (PMID 26483791, 2015). "Treatment of tumor cells by ICD-inducing cytotoxic compounds leads to a post-apoptotic release of HMGB1, which is recognized by TLR4 on DCs." (PMID 26483791, 2015). "Quantitative real-time PCR (qRT-PCR) showed that the HMGB1 mRNA level was significantly higher in BUC tissues compared with paired adjacent non-tumour tissues (5.390 ± 3.329 vs. 2.373 ± 1.485, P < 0.05, Fig. 1A1, A2)." (PMID 26239046, 2015). "Our results indicated release of at least three danger signals—Hsp70, Hsp90, and HMGB1—from tumor antigens." (PMID 26221615, 2015). "In initial experiments, we first sought to identify if recombinant human HMGB1 can induce sCLU from tumor cells." (PMID 26469759, 2015). "For instance, both HSP70 and CRT were demonstrated here to play a more essential role than HMGB1 on induction of ICD in test tumor cells." (PMID 26403780, 2015). "The in vivo studies demonstrated that combination of RT, DTIC and HT with zVAD-fmk induced the strongest tumor growth retardation in a HMGB1- and nucleotide-dependent manner." (PMID 25973681, 2015).